REN (renin)
Diseases named in the same sentence as REN in open-access papers (continued):
Sharing a sentence is not in itself a finding about the gene and the disease.
Insulin resistance (continued). "In addition, mechanisms such as insulin resistance, oxidative stress, systemic chronic low-level inflammation, and inappropriate activation of the renin–angiotensin–aldosterone system are also involved in developing proteinuria." (PMID 35966103, 2022). "The local and systemic factors of the adipose tissue, such as insulin resistance (IR), renin-angiotensin-aldosterone system (RAAS) activation, lipotoxicity, and interstitial fibrosis, may indirectly contribute to the development of CVD." (PMID 36589802, 2022). "With the progression of NASH, metabolic disorders, for example, dyslipidemia, insulin resistance, and glucose intolerance, would collectively advance the renin-angiotensin (RAS) system system and influence nitric oxide formation, which can facilitate the progression of DN." (PMID 36387855, 2022). "Moreover, insulin resistance is associated with the renin-angiotensin system (RAS), in which the initial action of renin cleaves angiotensinogen to angiotensin I (ANG I), then ANG I converts to ANG II by the angiotensin converting enzyme (ACE)." (PMID 36112580, 2022). "The cytokines released by adipose tissue by systemic and localized secretion would induce insulin resistance, renin-angiotensin-aldosterone system (RAAS) activation, lipotoxicity, and myocardial interstitial fibrosis, which was tightly related to several types of cardiovascular diseases." (PMID 36589802, 2022). "Insulin resistance and the resulting hyperinsulinemia may induce blood pressure elevation by the activation of the sympathetic nervous system and the renin-angiotensin-aldosterone system." (PMID 35350484, 2022). "Insulin resistance states and chronic hyperinsulinemia induce the local activity of the renin-angiotensin-aldosterone system, followed by the expression of angiotensin II receptors in vascular tissue, resulting in vessel wall hypertrophy, fibrosis, and reduced arterial elasticity." (PMID 39221025, 2022). "On the other hand, the effect of improving insulin resistance and regulating renin-angiotensin in the DASH diet may play a cooperate role in reducing SUA concentration and thereby reducing the risk of hyperuricemia." (PMID 36432539, 2022). "In addition, blood pressure can be elevated by activation of the renin-angiotensin-aldosterone system, the sympathetic nervous system, and mechanisms related to insulin resistance." (PMID 33679891, 2021). "The major pathophysiologic mechanisms underlying increased arterial stiffness in DM include hyperglycemia, insulin resistance, the formation of advanced glycation end products (AGEs), enhanced oxidative stress, chronic inflammation, and increased activity of the renin–angiotensin–aldosterone system." (PMID 33397376, 2021). "The renin-angiotensin-aldosterone system (RAAS) might contribute to the development of insulin resistance." (PMID 34067712, 2021). "Thus, lipid accumulation in these cells will lead to a cell dysfunction and injury by triggering inflammation, oxidative stress, impairment of renin–angiotensin–aldosterone activity, and insulin resistance." (PMID 34768854, 2021). "Renin, but not aldosterone, was associated with the Homeostatic Model Assessment for Insulin Resistance (β = .15), indicating insulin resistance." (PMID 32529242, 2020). "As FBG levels increase, hyperglycemia with insulin resistance, excessive weight and metabolic disorder may alter the renin-angiotensin in system, thereby raising blood pressure." (PMID 31280253, 2019). "Insulin resistance and activation of the renin-angiotensin-aldosterone system (RAAS) might provide potential pathophysiologic links between these clinical entities." (PMID 31511022, 2019). "In addition to stimulating the synthesis of blood cholesterol in the liver, adipose tissue promotes inflammation and oxidative stress, which lead to insulin resistance and higher production of renin-angiotensin-aldosterone system components." (PMID 29642188, 2018).
Insulin resistance (continued). "It has been suggested that the underlying mechanism of exaggerated MBPS may be explained by insulin resistance, increased sympathetic activity, and increased renin-angiotensin-aldosterone system activity." (PMID 30092787, 2018). "It has been shown that the major factors contributing to cardiac insulin resistance are oxidative stress, hyperglycemia, hyperlipidemia, dysregulated secretion of adipokines/cytokines, and inappropriate activation of renin-angiotensin II-aldosterone system (RAAS) and sympathetic nervous system." (PMID 30373519, 2018). "In patients with CKD, the dysregulation of calcium and phosphate metabolism induces vascular smooth muscle calcification, and CKD complications, such as renin-angiotensin-aldosterone system (RAAS) activation or insulin resistance, induce endothelial dysfunction and atherosclerosis." (PMID 28286758, 2017). "Moreover, it inhibits renin activity, suppresses the renin-angiotensin-aldosterone system, and affects nitric oxide levels, inflammatory parameters, angiogenesis, platelet aggregation, insulin resistance, and fasting glucose values." (PMID 29064392, 2017). "The renin-angiotensin-aldosterone system’s deleterious axis increases the production of inflammatory cytokines and raises oxidative stress; consequently, exacerbating insulin resistance and decreasing insulin secretion." (PMID 28098780, 2017). "The exact pathophysiology of diabetic cardiomyopathy is unknown, but metabolic changes such as hyperglycemia, dyslipidemia, insulin resistance, and activation of the renin-angiotensin system are thought to result in myocardial fibrosis." (PMID 28683825, 2017). "In insulin resistance and endothelial dysfunction, a hyperactivity of the renin-angiotensin-aldosterone system (RAAS) plays a crucial role, and therefore targeting it on a different molecular level benefits in improvement in insulin sensitivity and vascular function." (PMID 27413253, 2016). "Renin-angiotensin system (RAS) activation promotes oxidative stress which increases the risk of cardiac dysfunction in metabolic syndrome (MetS) and favors local insulin resistance." (PMID 28036029, 2016). "There may be several explanations on the effects of NAFLD on eGFR levels such as disturbed tumor necrosis factor system, imbalance of renin-angiotensin-aldosterone system, insulin resistance, and chronic inflammation." (PMID 26087253, 2015). "Vitamin D deficiency also predisposes patients with CKD to a high morbidity and mortality due to metabolic bone disease, atherogenesis, insulin resistance and renin-angiotensin-aldosterone system (RAAS) activation leading to chronic renal inflammation and immune dysfunction." (PMID 24719814, 2014). "Insulin resistance and/or abdominal obesity induce elevation of blood pressure due to sodium retention, sympathetic over-activity, vasoconstriction and activation of the renin-angiotensin system." (PMID 23711224, 2013). "Insulin resistance is detected in nearly 50% of hypertensive patients, and as a result of insulin resistance, hyperinsulinemia contributes to the elevation of blood pressure by promoting sympathetic nervous system and renin-angiotensin activities." (PMID 24072084, 2013). "The fructose-mediated increase in ROS via activation of the adipocyte renin-Ang II system may lead to adipocyte dysfunction and insulin resistance." (PMID 23762544, 2013). "We hypothesized that chronic systemic RAS activation via transgenic renin overexpression in the liver would lead to glucose intolerance and systemic insulin resistance." (PMID 23308073, 2012). "Inhibition of the renin-angiotensin system restored baroreflex sensitivity of the perinatal taurine-depleted rats to that of control groups, despite their hyperinsulinemia and insulin resistance." (PMID 20804606, 2010).
Insulin resistance (continued). "Besides life-style changes, the blockade of the renin-angiotensin system has been proposed as a useful alternative intervention to improve insulin resistance and decrease the number of new type-2 diabetes cases." (PMID 16959033, 2006). "Improvements in liver dysfunction may contribute to improved insulin resistance and uric acid levels, in addition, improvements in the renin–angiotensin–aldosterone system (RAAS) may lead to corrected glomerular capillary pressure, thereby demonstrating renal protective effects." (PMID 41356116, 2026). "Second, the renin‐angiotensin system may contribute to liver and kidney disease progression by increasing ectopic lipid deposition, proinflammatory cytokine production, and promoting insulin resistance." (PMID 37974383, 2024). "The renin–angiotensin system plays a central role in MetS, with enhanced activation of angiotensin II precursors, increased angiotensin II activity, and upregulated expression of angiotensin receptor 1 observed as a consequence of hyperglycemia and insulin resistance." (PMID 39330492, 2024). "We also found renin activity elevated in patients with DM, meanwhile activation of the renin-angiotensin-aldosterone system may play a significant role in the development of insulin resistance and diabetes." (PMID 35904746, 2022). "Studies have suggested that the mechanism by which low salt intake could induce insulin resistance and lead to T2DM is similar to that in high sugar intake diets, while in other studies, law salt intake could induce insulin resistance by activating the renin angiotension aldosterone system." (PMID 33819180, 2021). "Previous studies have shown that a direct renin inhibitor increased pancreatic islet function and upregulated insulin action on skeletal muscle glucose transport, further improving glucose intolerance and insulin resistance through the downregulation of tissue Ang II and Ang II type 1 receptor." (PMID 28700686, 2017). "In addition, the possibility of combination chemoprevention using renin-angiotensin system inhibitors and specific drugs for Mets (such as antidiabetic drugs, which improve insulin resistance) for preventing Mets-related colorectal carcinogenesis must also be explored." (PMID 24959250, 2014). "Recent findings, suggesting vitamin D being a modulator of both insulin resistance and the renin-angiotensin system and the renin-angiotensin system in local pancreatic islet structure and function, suggest that perhaps renal dysfunction and MetS may share common pathological pathways." (PMID 21860804, 2012). "AGTR1 (angiotensin II receptor type 1) is a key player in the renin-angiotensin system (RAS) that can increase blood pressure and insulin resistance while also inhibiting lipolysis, maintaining energy homeostasis, and reducing inflammation." (PMID 38246999, 2024). "Aberrant activation of the classic renin–angiotensin system (RAS) and intestinal micro dysbiosis adversely affect insulin resistance (IR), dyslipidemia, and other metabolic syndrome markers." (PMID 39086603, 2024). "The resultant overactivation of the renin-angiotensin-aldosterone system (RAAS) leads to systemic and vascular insulin resistance through insulin-mediated Glut-4 translocation and impairment of endothelial nitric oxide production." (PMID 37102024, 2023). "MetS is associated with insulin resistance, chronic inflammation, activation of oxidative and prothrombotic pathways, and deregulation of the renin-angiotensin axis, which may have negative impact on various physiological domains that contribute to the developing of frailty over time." (PMID 35893323, 2022). "KEGG analysis showed that DEGs were mainly enriched in “renin-angiotensin system,” “PPAR signaling pathway,” “complement and coagulation cascades”, and “insulin resistance”." (PMID 33539322, 2021).
Insulin resistance (continued). "Despite presenting with no biological activity, once broken down to angiotensin II (AngII) via a consecutive action of renin and ACE, it can induce insulin resistance via a cross-talk mechanism between insulin and AngII signaling cascade." (PMID 26682227, 2016). "Moreover, insulin resistance, sodium retention, excessive activation of the renin angiotensin aldosterone system, and increased arterial stiffness due to kidney function decline are pathways that might mediate the association of CKD with resistant hypertension." (PMID 26807712, 2016). "The roles of renin-angiotensin system (RAS) in insulin signaling pathway and insulin resistance have been well documented." (PMID 26682227, 2016). "Taken together, our data suggest therefore that the dysregulation of renin-angiotensin system played a key role in the fœtal programming effects of MDD on liver inflammation and fibrosis and insulin resistance." (PMID 27853271, 2016). "We also recapitulate LF can alleviate insulin resistance by inhibiting the NF-κB inflammatory pathway, activating the IRS/PI3K/Akt/Glut signaling pathway, and inhibiting the renin-angiotensin system to reduce the blood pressure, therefore improving the metabolic syndrome." (PMID 40313489, 2025). "Moreover, interactions among hyperinsulinemia, the sympathetic nervous system, the renin–angiotensin system (RAS), and altered adipokine and hepatokine profiles further amplify insulin resistance, ectopic lipid deposition, and systemic damage." (PMID 40725208, 2025). "In addition, dysregulation of the sympathetic nervous system and renin–angiotensin–aldosterone system in the context of ACS leads to increased stimulation of adrenergic and angiotensin II receptors and the occurrence of insulin resistance." (PMID 38336786, 2024). "On the contrary, TMAO, LPS, PS, and IS have been suggested to contribute to renal dysfunction by activating the renin–angiotensin–aldosterone system (RAAS) and the endothelin system, and then inducing insulin resistance, inflammation, oxidative stress, and fibrosis." (PMID 36361652, 2022). "This dependency may be due to the activation of the renin–angiotensin–aldosterone (RAA) system in type 1 diabetes and insulin resistance or hyperinsulinemia in type 2 diabetes patients." (PMID 36167527, 2022). "In addition to the regulation of blood pressure, the renin-angiotensin system (RAS) also plays a key role in the onset and development of insulin resistance, which is central to metabolic syndrome (MetS)." (PMID 32235782, 2020). "Angiotensin II activates renin-angiotensin-aldosterone system (RAAS) and affects the function of the pancreatic islets, resulting in islet fibrosis and reduced synthesis of insulin, and ultimately leading to insulin resistance." (PMID 27517947, 2016). "Serum levels of angiotensin-II, the active product of the renin-angiotensin system, were elevated in both SHRSP and SHRSP-ZF rats, but only the SHRSP-ZF rats developed insulin resistance, dyslipidemia, and hyperleptinemia and exhibited an increase in adipose tissue." (PMID 23860206, 2013). "Indeed, genetic deletion of AGT, ACE, renin, AT1, or AT2 protects rodents from diet-induced obesity and insulin resistance." (PMID 23308073, 2012). "REN, a key enzyme in the renin–angiotensin system (RAS), initiates the conversion of angiotensinogen to angiotensin I. Its elevated activity in T2D contributes to increased oxidative stress and inflammation, exacerbating insulin resistance and beta cell dysfunction." (PMID 39195477, 2024). "The dysregulation of the renin-angiotensin system is known to produce and/or favour most of the changes, which were observed in the iMDD/HF rats, including inflammation, increased expression of TGF-β1 and related markers of fibrosis, insulin resistance and central obesity." (PMID 27853271, 2016).
Insulin resistance (continued). "Therefore, activation states of the renin-angiotensin system contribute to AT1R stimulation and may support the occurrence of remodeling and insulin resistance in the heart." (PMID 24466104, 2014).
chronic kidney disease (320 papers, 2007 to 2026). Impairment of the renal function secondary to chronic kidney damage persisting for three or more months. "The characteristics of cluster 1 shown in both cohorts is consistent with previous reports suggesting a possible association of elevated aldosterone-to-renin ratio with older age, female and chronic kidney disease." (PMID 41473246, 2025). "A number of studies have reported that chronic kidney disease increases the risk of developing AF due to excessive extracellular fluid and toxins, and the activation of the renin-angiotensin-aldosterone system results in atrial remodeling." (PMID 37324618, 2023). "In recent years, a new drug has appeared that has raised hope in the treatment of hyperkalemia associated with the use of drugs acting on the renin–angiotensin–aldosterone system in patients with chronic renal failure." (PMID 34576158, 2021). "Metformin and renin-angiotensin system blockers were negatively associated with albuminuria and chronic kidney disease stages (p < 0.01)." (PMID 34134654, 2021). "Diabetic kidney disease (DKD) is the leading cause of end stage renal disease, where the increased activation of the renin‐angiotensin‐aldosterone system (RAAS) contributes to renal fibrosis." (PMID 30324679, 2019). "The underlying pathogenesis of chronic kidney disease involves an activated renin-angiotensin system and systemic inflammation which ultimately develop renal injury." (PMID 30996242, 2019). "The present study is aimed to investigate the potential modifier effect of REN gene polymorphisms on the progression of chronic kidney disease (CKD) in ADPKD." (PMID 26753721, 2016). "Vitamin D is a known suppressor of renin biosynthesis, and vitamin D deficiency has been associated with progression of chronic kidney disease (CKD)." (PMID 26109389, 2015). "Chronic kidney disease is characterized by Vitamin D deficiency and activation of the renin-angiotensin-aldosterone system." (PMID 26064952, 2015). "Diabetic kidney disease (DKD) remains the most common cause of chronic kidney disease and multiple therapeutic agents, primarily targeted at the renin-angiotensin system, have been assessed." (PMID 26239552, 2015). "We hypothesize that UUO-mediated cardiac hypertrophy may be caused by the activation of the renin–angiotensin–aldosterone system, hemodynamic alterations, and accumulation of uremic toxins in acute/chronic kidney disease." (PMID 40869420, 2025). "Renin is secreted by kidneys, plays a role for regulation of blood pressure and electrolyte balance and is associated with renal tubular dysgenesis, tubulointerstitial kidney disease and chronic kidney disease." (PMID 38791453, 2024). "Mineralocorticoid Receptor Antagonists (MRAs): Mineralocorticoid receptor activation due to the upregulation of renin and angiotensin axis causes activation of inflammatory factors and fibrosis, which contribute to the progression of chronic kidney disease as well as congestive heart failure." (PMID 37834846, 2023). "Nonetheless, the overactivation of the renin-angiotensin-aldosterone system caused by the CVDs may stimulate renal fibrosis and the progression to end-stage renal disease." (PMID 37529046, 2023). "Hyperkalemia is common in patients treated with renin–angiotensin–aldosterone system inhibitors (RAASis), and it represents the main cause of the large gap reported between guideline recommendations and real-world practice in chronic kidney disease (CKD)." (PMID 35224054, 2022). "Mutations in the REN gene lead to intracellular accumulation of abnormal protein, resulting in apoptosis of renin-producing cells in the juxtaglomerular apparatus with consequent nephron loss and progressive chronic kidney disease (CKD)." (PMID 28701203, 2017). "However, FGF21 levels have previously been associated with activity of the renin-angiotensin system in patients with end-stage renal disease on dialysis." (PMID 25890271, 2015).